IL6 (interleukin 6)
Diseases named in the same sentence as IL6 in open-access papers (continued):
Sharing a sentence is not in itself a finding about the gene and the disease.
endometriosis (continued). "The research found the three proinflammatory cytokines interleukin (IL)‐1, IL‐6 and tumor necrosis factor (TNF)‐alpha, are all involved in the development of endometriosis." (PMID 30828987, 2019). "Quinagolide, another non-ergot-derived dopamine agonist, reduced the levels of both IL-6 and VEGF in peritoneal fluid and was shown to be of potential use for the treatment of endometriosis-induced endometriosis in a rat model." (PMID 30402122, 2018). "In conclusion, microRNA Let‐7b treatment of endometriosis resulted in decreased oestrogen signalling (ER and Cyp19A1), decreased KRAS and decreased inflammatory signalling (IL‐6)." (PMID 30063121, 2018). "Decreased gene expression was noted in several genes known to promote endometriosis growth including ER‐α, ER‐ß, Cyp19a, KRAS 4A, KRAS 4B and IL‐6." (PMID 30063121, 2018). "On the other hand, neutralization of IL-6 with antibody decreased the expression of CD163 and IL-10 in macrophages in an endometriosis condition, reflecting prevention of macrophage polarization toward an M2 phenotype." (PMID 30276219, 2018). "IL-6 and TNF-α, activate intracellular signal molecules to induce production of O2•- and H2O2 during the pathogenesis of endometriosis via the respiratory burst NADPH oxidase system." (PMID 30555421, 2018). "Elevated serum IL-6 and TNF-α levels indicative of increased inflammatory activity have been observed in patients with endometriosis." (PMID 30555421, 2018). "In another study where, a model of endometriosis was established and up-regulation of fibrotic markers (TGF, CTGF, and collagen-1) and inflammatory cytokines (IL-1 and IL-6) were recorded." (PMID 28883083, 2017). "The levels of the inflammatory cytokines IL-6, IL-8, IL-1b, IFN-γ, and TNF-α increase in the PF of patients with endometriosis, which is consistent with the elevated levels noted in the serum." (PMID 27294113, 2016). "Endometriosis-related CCC is thought to be a chronic inflammatory disease, characterized by increased production of pro-inflammatory cytokines such as IL-1, IL-6, IL-8, IL-10, and TNF-α." (PMID 25366985, 2014). "In the peritoneal cavity activated macrophages are the major source of IL-1β, IL-6, IL-8 and TNF-α and altered expression of these proinflammatory cytokines has been described in the peritoneal fluid of women with endometriosis." (PMID 24587003, 2014). "Many studies on the role of other biomarkers in endometriosis (e.g., TNF-α, IL-6, VEGF, and CRP) have been conducted recently." (PMID 25006484, 2014). "Peritoneal macrophages are known to express inflammatory cytokines, such as IL-6, IL-1β and tumor necrosis factor alpha (TNF-α) and to be increased in number and more activated in patients with endometriosis." (PMID 24039864, 2013). "IL-6, IL-12 and VEGF are involved in the development of endometriosis with excessive endometrial angiogenesis, and overexpressions of VEGF and PDGF have been linked to different types of malignancies and tumors." (PMID 23201926, 2012). "Its production is stimulated by pro-inflammatory cytokines such as IL-6, IL-1 and TNF-alpha which are up-regulated in women with endometriosis when compared to controls." (PMID 21827658, 2011). "In conclusion systemic EGF, MIF, IL-6, and SOM might have a contribution to the development and symptomatology of endometriosis, but further rigorous and standardized research is needed to clarify their roles in disease development." (PMID 40724945, 2025). "Patients with endometriosis exhibit systemic monocyte activation: their spontaneous and induced production of proinflammatory cytokines TNF-α, IL-6, and IL-8 is elevated with normal levels of anti-inflammatory IL-10, indicating a proactive state of the monocyte-macrophage system." (PMID 41488658, 2025). "Notably, serum concentrations of IL6 and IL8 in endometriosis patients are higher than in healthy women, and PGE2 production is also elevated in these patients." (PMID 40802848, 2025).
endometriosis (continued). "Platelets and other inhibitory cytokines, IL-6, IL-16, IL-17, IL-1β, IL-10, and TGF-β, are found in the peritoneal fluid in patients with endometriosis and function to prevent the NK cells from degranulation and producing interferon (IFN)-γ, impairing the NK cell function." (PMID 40747182, 2025). "One study evaluated follicular IL-6 levels, which are associated with inflammatory responses, and reported that despite elevated IL-6 levels, the follicular AMH levels in the endometriosis group were not lower than those in the control group." (PMID 40648868, 2025). "However, the peritoneal compartment exhibited a distinct immune–metabolic profile: IL-6, hepcidin, and ferritin levels were higher in HGS-OC, whereas ROS and free iron were elevated in endometriosis." (PMID 40723209, 2025). "Furthermore, dysregulated IL-6 signaling is often observed in conditions like polycystic ovary syndrome (PCOS) and endometriosis, linking chronic inflammation to female infertility." (PMID 40426899, 2025). "Based on our data and the existing literature, IL-1β, IL-6, and IL-8 do not appear to be reliable predictive serum biomarkers for endometriosis, as they show high interindividual variability." (PMID 40724945, 2025). "We found that the M1/M2 ratio was significantly and directly related to IL-6, hepcidin, ferritin, and ROS levels in OC patients but not in women diagnosed with endometriosis." (PMID 40723209, 2025). "Dairy, which contains progesterone, estrogen, calcium, vitamin D, and anti-inflammatory components, may lower the chance of developing endometriosis by decreasing inflammatory markers such as TNF-a, reactive oxygen species, and interleukin-6 (IL-6)." (PMID 40565701, 2025). "Several studies have documented elevated IL-6 concentrations in follicular fluid, peritoneal fluid, or serum in women with endometriosis compared to controls (e.g., IL-6 in FF in ENDO vs. non-ENDO: 152.3 vs. ~19.9 pg/mL)." (PMID 41463303, 2025). "It has also been shown that IL-6 levels are higher already in women with stage I-II endometriosis than in women without endometriosis." (PMID 40507929, 2025). "It has been reported that IL-6 levels in the peritoneal fluid of patients with minimal–mild endometriosis do not correlate with pain; however, this relationship has not been investigated in serum or tissues obtained from patients with DIER." (PMID 40724945, 2025). "IL6, a pro-inflammatory cytokine that has been reported to be highly expressed in ovarian endometriosis, dominated pathways of TNF signaling and NF-κB activation, which are hyperactive in endometriosis and implantation failure." (PMID 41227338, 2025). "They found elevated levels of pro-inflammatory markers, including TNF-α, IL-6, and IL-1β, in the control group rather than in those with endometriosis." (PMID 39767772, 2024). "Additionally, peritoneal macrophages in women with endometriosis exhibit an overexpression of both ERα and ERβ, along with elevated levels of inflammatory cytokines, including VEGF, IL-6, and TNF-α." (PMID 38612685, 2024). "Elevated levels of pro-inflammatory cytokines, such as interleukin-6 (IL-6), interleukin-1beta (IL-1β), tumor necrosis factor-alpha (TNF-α), and prostaglandin E2 (PGE2) have been consistently identified in women diagnosed with endometriosis." (PMID 39257907, 2024). "Furthermore, the study suggested that women with endometriosis-related infertility presented increased levels of TNF-α, IL-1, IL-6, IL-10, TGF-β1, and IL-8 in peritoneal fluids." (PMID 38813329, 2024). "In contrast, IL-6 levels in the peritoneal cavity were not significantly different (1.0 vs. 1.2; p = 0.0561) between the control and ectopic endometriosis groups." (PMID 38612685, 2024). "In this study, we hypothesized that the inflammatory environment, specifically IL-6, in the peritoneal cavity of women with endometriosis could upregulate miR-21 via STAT3, leading to an increase in fibrosis in endometriosis." (PMID 39201680, 2024).
endometriosis (continued). "Moreover, a previously published study identified important proangiogenic factor such as vascular endothelial growth factor (VEGF), IL-1β, IL-6 and IL-8 as well as TNF-α played important roles in the vascularization process in endometriosis." (PMID 37033937, 2023). "Notably, inhibition of miR-138 expression promotes inflammation by increasing levels of TNF-α, IL-1β, IL-6, and IL-18 through activation of the NF-κB signaling pathway and VEGF in endometriosis." (PMID 37834449, 2023). "IL-6/soluble IL-6 receptor (sIL-6R) signaling dysfunction leads to the persistent activation of STAT3 and NF-κB, which induces the collagen synthesis of ESCs, contributing to the fibrosis of endometriosis." (PMID 36865552, 2023). "Moreover, TNFα and IL-1β activate the NK-κB signaling pathway, which in turn controls the expression of cytokines and chemokines such as IL-1, IL-6, IL-8, TNF-α, as well as ICAM-1 able to boost inflammation and COX-2 expression in endometriosis implants." (PMID 37447296, 2023). "G-CSF and IL-6 regulate neutrophils through STAT3 pathways and alter the expression of angiogenesis-related genes (Mmp9, Bv8, and Trail), which are involved in the establishment of early endometriosis." (PMID 36762287, 2023). "Inflammatory cytokines (interleukin-1β (IL-1β), interleukin-6 (IL-6), insulin-like growth factor (IGF-1) and tumour necrosis factor-α (TNF-α) are observed to be at a higher concentration in the peritoneal fluid of people with endometriosis." (PMID 38002684, 2023). "The level of IL-6 in FF was higher in women with proven endometriosis; these results are in line with previous studies reporting altered levels of IL-6 in FF in endometriosis patients with or without ovarian stimulation." (PMID 36902616, 2023). "Endometriosis patients displayed increased production of pro-inflammatory cytokines IL-1 and IL-6 by PBMCs compared to those without endometriosis." (PMID 38139822, 2023). "Moreover, the decrease of NK cytotoxicity in patients with endometriosis is suggested to be affected by cytokines (TGF-β, IL-6, and IL-15) in the peritoneal fluid." (PMID 37138868, 2023). "Although the biological mechanisms that induce the expression of TF and IL6 are not fully understood, they may be related to genetic alterations of OCCC and the endometriosis-related tumor microenvironment." (PMID 35565252, 2022). "A study pointed out that endometriosis patients can be differentiated from those without by measuring their relative serum IL-6 and PF TNF-α levels." (PMID 35592328, 2022). "In fact, the present study revealed that vaginal mucosa and endometriotic cells responded to increased levels of IL-6, IL-8, IL-1β, and TNF-α when challenged by Candida albicans or by LPS, and these cells present a pivotal role in the inflammatory process in endometriosis and leiomyoma." (PMID 35164046, 2022). "In addition, inflammatory cytokine concentrations like IL-1, IL-6, and TNF-α were elevated among endometriosis patients." (PMID 35592328, 2022). "Inflammation-related pathways such as IL6-JAK/STAT3 signaling, inflammatory response, interferon α response, interferon γ response, and TNFα signaling via NF-κB, were found to be significantly upregulated in patients with endometriosis." (PMID 36339397, 2022). "Endometriotic cells treated with TNF‐α activate peritoneal macrophages via pro‐inflammatory cytokines such as IL‐6 and MCP‐1, which has a vital role in initiating, progressing, and protecting endometriosis through the promotion of invasion and proliferation of endometriotic cells." (PMID 36310658, 2022). "The global expression profile enriched critical pathways already related to the endometriosis condition, such as PI3K signaling via AKT to mTORC1, mTORC1 signaling, TNFA signaling via NFkB, IL6 STAT3 signaling, TGF beta signaling, and hypoxia via HIF1A targets." (PMID 36232817, 2022).
endometriosis (continued). "The proposed panel of inflammatory markers, especially IL-6, PRL and CA 125, may become a useful tool to identify women with advanced endometriosis who could qualify for treatment." (PMID 33669013, 2021). "Such analysis determines whether the set of concentration values of CA 125, IL-6 and PRL can be used to differentiate serum samples in a way that reflects clinical characteristics typical for endometriosis." (PMID 33669013, 2021). "Significant differences were also observed in the concentrations of IL-6, hs-CRP and PRL when the non-endometriosis group (median values: 1.93 pg/mL, 0.99 mg/L and 22.78 ng/mL, respectively) was compared with the group of healthy women (p = 0.010, p = 0.037 and p < 0.001, respectively)." (PMID 33669013, 2021). "Proinflammatory cytokines, such as IL-1, IL-6, and TNF-α, can activate NF-κB, which induces inflammatory cell infiltration and increases the secretion of cytokines, stimulating the NF-κB signaling pathway and forming a positive feedback loop in endometriosis." (PMID 34266426, 2021). "Serum concentrations of IL-1β, IL-6, hs-CRP, IgG, YKL 40 and PRL, in comparison to the well-known CA 125 levels, were studied with the aim of identifying an additional noninvasive inflammatory marker or set of markers characteristic for endometriosis." (PMID 33669013, 2021). "This study aims to investigate follicular fluid (FF) concentration of interleukin (IL)-3, IL-5, and IL-6 in women with and without endometriosis." (PMID 35571503, 2021). "Additionally, crocin (25 mg/kg) mitigated VEGF, IL-6, IFN-γ, and TNF-α levels in a mouse model of endometriosis." (PMID 34956439, 2021). "Additionally, it has been observed that estrogen-ER interaction can regulate the production of IL-6 and TNF-α of lipopolysaccharide (LPS) activated pMφ from patients with endometriosis." (PMID 34639133, 2021). "Previous studies have demonstrated that the levels of pro-inflammatory cytokines IL-6, TNF-α, IL-1β, and IL-17 in the localized lesion (ectopic endometrium and peritoneal cavity) and circulation (serum) were significantly increased in women with endometriosis." (PMID 33815277, 2021). "Most of the previous studies have evaluated the concentration of interleukin-5 (IL-5) and IL-6 in the peritoneal fluid (PF) or serum of women with endometriosis and not in the follicular fluid (FF)." (PMID 35571503, 2021). "Also, significant increase in the levels of IL-6, IL-8 and MIF protein in FF of endometriosis group was detected in comparison with normal women (p<0.05)." (PMID 33209739, 2020). "The single levels of inflammatory cytokines IL‐1, IL‐6 and IL‐8 do not reflect the pathological development of endometriosis, but combined usage has the potential to mark diseases." (PMID 32960511, 2020). "Thus, these inflammatory factors (IL-6, IL-10, IL-13, and TNF-α) can be used as essential reference indexes for endometriosis diagnosis complicated with infertility." (PMID 33354460, 2020). "This dichotomous response may indicate that IL6 and IL8 are induced through separate mechanisms from MCP1 in endometriosis." (PMID 33233463, 2020). "Peritoneal macrophages from patients with endometriosis display increased activation of the pro-inflammatory transcription factor NF-κB and enhanced protein expression of pro-inflammatory cytokines such as TNF-α, IL-6, IL-1β, and TGF-β." (PMID 32145751, 2020). "Genistein could regulate estrogen receptor-α and estrogen receptor-β, and reduce the TNF-α, IL-6, VEGF, and HIF-1α levels in ectopic lesions in the endometriosis murine model." (PMID 32210799, 2020). "Previous studies have showed that IL-1β, IL-6, and TNF-α are increased in women with endometriosis." (PMID 32151056, 2020). "Comparable serum IL-6 levels were previously reported in women with and without endometriosis, while other investigators have reported elevated levels of IL-6 in endometriosis patients compared with normal ovaries." (PMID 32042020, 2020).
endometriosis (continued). "Interlieukin-10 (IL-10, IL-6, IL-8, COX2 (cyclooxygenase-2), VEGF (vascular endothelial growth factor) and tumor necrosis factor α (TNF-α) have been observed to be increased in the peritoneal fluid of endometriosis." (PMID 32244563, 2020). "Similarly, IL-1β, IL-6, TNF-α, and prostaglandin E2 (PGE2) were found to be rich in the peritoneal fluid of women with endometriosis." (PMID 31636643, 2019). "Notably, innate cellular chemoattractants (IL-12, I-309/CCL1, Eotaxin, MCP-1, IL-6, IL-8, and IFN-γ) were almost exclusively elevated in endometriosis patients with the sole exception of the neutrophil chemoattractant ENA-78/CXCL5." (PMID 31333337, 2019). "For example, levels of pro-inflammatory cytokines IL-1β, IL-6, IL-8, IFN-γ, and TNF-α are elevated in peritoneal fluid and serum of patients with endometriosis and could be used as non-invasive markers of the disease." (PMID 32063886, 2019). "A prospective cohort study on women with endometriosis and those with pelvic pain but without the diagnosis of endometriosis showed that the serum and peritoneal fluid levels of IL-6, miR-122, and miR-199a were significantly higher in the former." (PMID 30627562, 2018). "In patients with endometriosis, the level of miR-23b decreased significantly, the levels of IL-4 and IL-6 increased remarkably compared with that in patients without endometriosis." (PMID 29901577, 2018). "One study determined that the follicular fluid of naturally matured follicles (without gonadotropin stimulation) in endometriosis patients had higher IL-1β and IL-6." (PMID 30104541, 2018). "Of a number of proinflammatory cytokines, two have been established as potentially useful for diagnostics, IL-6 and TNF-α, which were found to be correlated with endometriosis and to be effective in diagnosing endometriosis in serum and peritoneal fluid as well as in menstrual effluents." (PMID 28487810, 2017). "A significantly increased secretion of TNF-α and IL-6 in the culture media of peritoneal macrophages of endometriosis patients was found in response to E2 compared to nontreated macrophages." (PMID 26198055, 2015). "Using a surgically induced endometriosis model, we first showed that treatment with LXA4 reduced the volume of endometriotic lesions in part by attenuating pro-inflammatory (IL-1β and IL-6) and pro-angiogenic (VEGF) mediators in endometriotic lesions and PFCs." (PMID 24587003, 2014). "Significantly higher IL-6 and IL-10 levels were found in moderate-to-severe but not in minimal-to-mild endometriosis as compared to controls." (PMID 23843796, 2013). "NF-κB-activated macrophages express proinflammatory, growth, and angiogenic factors, such as inducible Nitric Oxide (iNOS), cyclooxygenase-2 (COX-2), IL-1, IL-6, IL-8, TNF-α, and vascular endothelial growth factor (VEGF), which contribute to endometriosis pathogenesis and possible carcinogenesis." (PMID 24039864, 2013). "For instance, such correction was absent in three of the nine reviewed papers investigating IL-6 as a biomarker for endometriosis, despite evidence that levels are known to change throughout the cycle." (PMID 21827658, 2011). "Significantly, IL-6 has been shown to be a possible nonsurgical marker for predicting the development of endometriosis." (PMID 19019211, 2008). "In addition, they also produce some pro-inflammatory cytokines like IL-6, IL-17, and IFN-γ, which also play a role in the pathogenesis of endometriosis by creating an inflammatory environment and recruiting other cells, including macrophages, to enhance the growth of the lesion." (PMID 40747182, 2025). "Furthermore, inflammatory cytokines, including IL-6, IL-8, CA-125, and TNF-α, are consistently elevated in women with endometriosis, suggesting their involvement in disease progression and highlighting their potential utility as biomarkers for non-invasive diagnosis." (PMID 40362218, 2025).